KIF4B (kinesin family member 4B)
Description:
Iron-sulfur (Fe-S) cluster binding motor protein that has a role in chromosome segregation during mitosis (By similarity). Translocates PRC1 to the plus ends of interdigitating spindle microtubules during the metaphase to anaphase transition, an essential step for the formation of an organized central spindle midzone and midbody and for successful cytokinesis (By similarity). May play a role in mitotic chromosomal positioning and bipolar spindle stabilization (By similarity).
Tractability: PROTAC: UniProt records ubiquitination sites on it; ubiquitination databases record sites on it.
Gene: Protein-coding gene on chromosome 5 (155,013,755 to 155,018,141, forward strand). Ensembl gene ENSG00000226650.
Subcellular location: Nucleus matrix; Cytoplasm, cytoskeleton
Subcellular location (Human Protein Atlas): Midbody; Nucleoplasm; Acrosome; Equatorial segment; Mid piece; Principal piece
Pathways (Reactome):
Developmental Biology: Recycling pathway of L1
Hemostasis: Kinesins
Immune System: MHC class II antigen presentation
Vesicle-mediated transport: COPI-dependent Golgi-to-ER retrograde traffic
Gene Ontology:
Molecular function: ATP binding; microtubule binding; microtubule motor activity
Biological process: mitotic cytokinesis; mitotic spindle midzone assembly; mitotic spindle organization; spindle elongation; microtubule-based movement
Cellular component: cytosol; microtubule associated complex; nuclear matrix; cytoskeleton
Genetic constraint (gnomAD): Loss-of-function variants: 63 observed, 75.49 expected, observed/expected ratio (o/e) 0.83, 90% interval 0.68 to 1.03. The upper end of that interval is the gene's LOEUF score, 1.03, which puts it in group 4 of 6, group 1 being the genes least tolerant of losing a copy. Missense variants: 1,357 observed, 1,515.3 expected, observed/expected ratio (o/e) 0.9, 90% interval 0.86 to 0.94. Synonymous variants: 489 observed, 554.7 expected, observed/expected ratio (o/e) 0.88, 90% interval 0.82 to 0.95.
Homologues: Orthologues: macaque KIF4B (91% identical), guinea pig KIF4B (79% identical), mouse Kif4-ps (76% identical), rat Kif4b (74% identical). Paralogues in human: KIF4A (94% identical), KIF21A (32% identical), KIF21B (31% identical), KIF27 (25% identical), CENPE (25% identical), KIF7 (24% identical), KIF15 (21% identical), KIF13A (20% identical), KIF13B (20% identical), KIF5A (20% identical), KIF16B (19% identical), KIF1B (19% identical), and 29 more.
Diseases named in the same sentence as KIF4B in open-access papers:
KIF4B is named in the same sentence as 3 diseases in open-access papers, as found by Europe PMC text mining. Sharing a sentence is not in itself a finding about the gene and the disease. The quoted sentences say what the papers report.
pancreatic cancer (1 paper, 2018). "We report a remarkable long-term remission in a patient with advanced pancreatic cancer, who received an individualized four peptide vaccine based on in silico predicted peptide motifs from the two sole mutations in his cancer, i.e. in the proteins RIM1 and KIF4B." (PMID 29409514, 2018).
tumor (3 papers, 2018 to 2023). "The recurrent ASE genes in tumor samples include Chromosome-Associated Kinesin KIF4B, spindle and kinetochore associated complex subunit 3 (SKA3) and so on." (PMID 30538721, 2018).
KIF4B also shares sentences with these, for which no sentence is quoted: cancer (2 papers).